GLI1 (GLI family zinc finger 1)
Diseases named in the same sentence as GLI1 in open-access papers (continued):
Sharing a sentence is not in itself a finding about the gene and the disease.
tumor (continued). "GLI (GLI1 and GLI2), as a crucial transcription factor in the Hedgehog signaling pathway, regulates the transcription of multiple downstream target genes and promote tumor progression." (PMID 29899333, 2018). "By IHC, we found Gli1 was positively expressed in 17 out of 20 HER2 positive tumor tissues, while in 28 out of 47 HER2 negative tumors tissues, fourfold table chi-square test showed the expression level of Gli1 and HER2 was related (P = 0.043)." (PMID 29321573, 2018). "In resistant tumours lacking activating mutations in SMO, they found that GLI1 participates in a complex with SRF and MKL1 which promotes enhanced transcription of HH pathway target genes." (PMID 30068568, 2018). "In tumor ALI organoids, AY9944 and GANT61 significantly inhibited GLI-1 protein expression." (PMID 29642386, 2018). "GLI1 has been demonstrated to be a mediator of the SHH signal in vertebrates by binding to the promoter region of several target genes involved in different cellular processes, such as G1 cell cycle progression, tumor formation, and progression." (PMID 30423843, 2018). "Consistent with their transcriptional potential, GLI1-6A and GLI1-WT but not GLI1-6D increased cell proliferation in vitro and tumor growth in nude mice." (PMID 29662197, 2018). "In general, the incubation of the primary murine tumor cells with vismodegib, sonidegib, or HhAntag significantly reduced the expression of the Hh target Gli1, but not of Hhip." (PMID 30319965, 2018). "The results showed that Gli1 expression significantly shortened the survival no matter the patients’ age, the size of tumor, differentiation, venous invasion or neural invasion (P > 0.05)." (PMID 29321573, 2018). "Furthermore, IHC analysis identified that the tumours from injection of Caov3 SHH-OE cells alone and Caov3 NC cells alone barely expressed Ki-67, stromal Gli-1 and α-SMA." (PMID 28978035, 2017). "For instance, Gli1 was shown to correlate with markers of EMT and highly express in the claudin-low breast CSCs, and knockdown of Gli1 resulted in reduced claudin-low breast CSC's viability, motility, clonogenicity, and self-renewal as well as tumor growth in orthotopic xenografts." (PMID 28356914, 2017). "The results of the present study indicated the gene expression of these important factors in the Hedgehog signaling pathway, such as DHH, GLI1, and PTCH1, was changed by the knockdown of AE1, suggesting that AE1 regulates the tumor behavior of ESCC via this pathway." (PMID 28160546, 2017). "Next, IHC was performed to measure the expression of SMO, GLI1, and KI67 in tumor tissue." (PMID 29254217, 2017). "The remaining 187 articles were further assessed by screening the abstracts, among which 166 articles were excluded due to non-Gli-1-related human studies, not test in tumor tissues." (PMID 27634907, 2016). "Nevertheless, the prognostic impact of Gli1 presence in solid malignancies remains in controversy, despite an overwhelming majority of evidence has explored a negative prognostic value of Gli1 over-expression across miscellaneous neoplasms." (PMID 26899488, 2016). "In consideration of the relationship between tumor metastasis and EMT, the abnormal activation of Gli-1 may contribute to a potential high malignancy degree of cancer." (PMID 27634907, 2016). "Likewise, the results showed that most LAC cell lines (except for A549) showed a significantly reduced HHIP, but comparable GLI1 and SHH mRNA levels as compared to non-tumor lung epithelial cells BEAS-2B or NL20." (PMID 27015549, 2016). "Neither sex, history of nicotine or consumption of alcohol, age, tumor stage, n-status nor concomitant chemotherapy influenced expression of Gli-1 or Gli-2." (PMID 27918595, 2016). "Taking into consideration that OPN is a known GLI1 transcriptional target 113, a potential vicious cycle can be envisaged, amplifying OPN‐mediated heterotypic signaling and expansion of stem cell‐like tumor subpopulation in TNBC." (PMID 27539549, 2016).
tumor (continued). "In vitro analysis showed that most LAC cell lines did not express significantly enhanced SHH or GLI1 than non-tumor lung epithelial cells, but had a remarkably reduced HHIP expression." (PMID 27015549, 2016). "The meta-analysis indicates that Gli-1 is overexpressed in tumor tissue in comparison with the normal tissue, which is consisted with other studies." (PMID 27634907, 2016). "Knockdown of GLI1 did not have an effect on hypoxia-induced HIF1α expression, but completely eliminated the hypoxia-induced vimentin and E-cadherin expression and tumor cell invasiveness." (PMID 26053182, 2015). "GLI1-induced expression of EMT markers in response to genotoxic lesions suggests a functional link between HH signaling and DDR, and transformation of precursor lesions to tumor development." (PMID 26633513, 2015). "Furthermore, validating the synergistic effect of both GLI1 and DNMT inhibitors in various tumor cells will give new treatment options." (PMID 26633513, 2015). "The role of the stromal Hh pathway in tumor maintenance was clearly demonstrated in pancreatic cancer, where tumor growth was reduced when growing in a microenvironment lacking Gli1 compared to the wild-type." (PMID 26184317, 2015). "Together, these results show that PCAF can induce cell apoptosis by modulating a GLI1/Bcl-2/BAX axis that in turn suppresses HCC progression, and suggest that 5-FU may exert a stronger anti-tumor effect in patients with PCAF expression in HCC tumors." (PMID 25855960, 2015). "The immunohistofluorescence analyses of PC3 tumor specimens have indicated that 50 mg/kg GDC-0449, or 5 mg/kg docetaxel alone, significantly inhibited the GLI-1 expression in PC3 xenografts as indicated by a decrease of GLI-1-positive red staining relative to untreated PC3 tumors used as control." (PMID 25682877, 2015). "Thus, combined GLI1/2 and PI3K/mTOR inhibition represents a promising novel approach for synergistic apoptosis induction and tumor growth reduction with implications for new treatment strategies in RMS." (PMID 25749378, 2015). "It was reported that the mechanisms of Shh-Gli1 signaling pathway promoting malignant tumors involved in many aspects of malignant biological behaviors but its main role in tumors is to promote EMT and maintain tumor stem cells." (PMID 25072505, 2014). "This indicates GLI1 may play a dual role in PDAC, acting as an oncogene in the early stages of disease and a tumor-suppressor in the late stages." (PMID 25352983, 2014). "The results of the present study show that Shh and Gl-1 are more highly expressed in NSCLC tissues than in normal counterpart tissues.Gli1 protein was detected mainly in tumor tissues, but occasionally in nontumor tissues." (PMID 25141859, 2014). "Amplification of SMO was found in one tumor, but this tumor did not exhibit elevated expression of SMO or GLI1." (PMID 24368541, 2013). "The mechanism by which NRP2 signalling promotes tumour initiation involves stimulation of the α6β1 integrin, focal adhesion kinase-mediated activation of Ras/MEK signalling and consequent expression of the Hedgehog effector GLI1." (PMID 23436775, 2013). "Tumor epithelial expression of Shh, Smo and Ptch was up-regulated compared to the non-neoplastic epithelium, whereas stromal Ptch, Smo and Gli1 were down-regulated in the tumor tissue." (PMID 23880852, 2013). "Together these findings support a novel role for GLI1 in HCC pathogenesis and suggest tumor recurrence as one of the biological features that may be modulated by this transcription factor." (PMID 23185371, 2012). "Furthermore, we analyzed splicing profiles of two additional genes: GLI1 oncogene and CEACAM1 tumor suppressor whose disturbed splicing is known to contribute to tumor progression." (PMID 21082031, 2010). "However, we were unable to find any significant correlation between GLI1 and PTCH1 expression in the cell lines and tumor samples (p = 0.07)." (PMID 21059263, 2010).
tumor (continued). "Most of the primary tumor samples showed high expression levels of the GLI1 protein but these samples did not express Cyclin D2." (PMID 21059263, 2010). "Real-time PCR confirmed the results from in-situ hybridization showed that normal tissues had low or no level of GLI1 expression whereas tumor tissues had elevated levels of GLI1." (PMID 19943941, 2009). "In contrast, in the Gli-1-null or cytoplasmic expression or no residual tumour group (n=62), recurrences were found in 22 patients (in the liver, bone, lung, neck lymph nodes, and thyroid gland)." (PMID 18475300, 2008). "Gli-1 expression was absent in 12 tumours (17.4%) but present in 31 tumours (44.9%), seven (10.1%) of which were nuclear and 26 (37.7%) of which were cytoplasmic." (PMID 18475300, 2008). "Kaplan–Meier analysis suggested that the prognosis was particularly unfavourable for patients with Gli-1 nuclear expression in their primary tumours, compared with the Gli-1-null or cytoplasmic expression patients or those with no residual tumour." (PMID 18475300, 2008). "The data reported here clearly shows that a net increase in Hh signaling, as measured by expression of the conserved Hh target genes Ptc and Gli1, is not a feature of tumor development in the LADY mouse." (PMID 17343742, 2007). "Given the proximity of the DDIT3 gene to GLI1, the use of a DDIT3 split probe may be useful in identifying the possibility of GLI1 rearrangement in neoplasms that display a phenotype or morphology typical of a neoplasm with GLI1 alteration." (PMID 38275873, 2024). "Moreover, GLI1, GLI2, and GLI3 were significantly expressed in ten, ten, and thirteen tumor stages, respectively, suggesting their involvement in tumor progression." (PMID 38498906, 2024). "In addition, the Shh-Gli1 pathway induces the expression of the transcription factor SNAIL not only to regulate the epithelial mesenchymal transition (EMT) process, but also to promote the self-renewal of tumor stem cells." (PMID 39852882, 2024). "Despite the diagnostic implications that the overlap of genetic alterations in neoplasms with changes in genes within the 12q13-15 region could create, the discovery of coamplifications of MDM2 with CDK4 and GLI1 offers new therapeutic targets in neoplasms with MDM2/CDK4 amplification." (PMID 38275873, 2024). "Moreover, low expression of GLI1 was detected in the non-neoplastic oral mucosa near the tumour, and the clinical stage of the patients was also closely linked with the expression level of SMO." (PMID 39234399, 2024). "Following our findings that PTCH1 reduces autophagic flux through its CTD, we hypothesised that its interaction with ATG101 is important for the tumour suppressor activity of PTCH1, which is mainly ascribed to its function to reduce GLI1 levels via regulation of the canonical Hh pathway." (PMID 36672319, 2023). "Upactivation of the HH signaling pathway in cancer cells induces GLI1 and SHH overexpression, which increases the expression of proangiogenic factors, including VEGF-A, MMP-2, MMP-9, heparanase, and cysteine-rich angiogenic inducer 61 (Cyr61), in different tumor cells." (PMID 37626893, 2023). "Our design leaves something to be desired; tumor growth in nude mice could be studied with or without the treatment of animals using a Gli1 inhibitor; for example, GANT61." (PMID 36900220, 2023). "Overexpression of Gli1 in glioblastoma cell lines results in increased tolerance to TMZ, whereas pharmacological inhibition of Hh signaling using GANT61 and cyclopamine resensitizes cells to chemotherapy, and treatment with cyclopamine reduced tumor burden in vivo." (PMID 37954979, 2023). "However, GLI1 inhibition didn’t correlate with tumour responses, pointing at GLI1 as a good pharmacodynamic marker for SMO inhibitors but not for tumour response." (PMID 36765685, 2023).
tumor (continued). "Furthermore, overexpression of GLI1, GLI2, PTCH1, and SMO was correlated with a higher histological grade of the tumor, what may suggest that HH signaling plays a key role in HNSCC malignancy." (PMID 37626893, 2023). "Furthermore, we present evidence that in these irradiated tumor cells, Treacle ribosome biogenesis factor 1 (TCOF1), a nucleolar protein that is important in ribosome biogenesis, facilitates nucleolar translocation of GLI1." (PMID 37380890, 2023). "Importantly, this decrease in tumor growth is only seen in a HH-sensitized model (when host mice lack one copy of Gli1), further demonstrating that severe inhibition of HH, not slight reduction, is necessary to reduce tumor growth." (PMID 35867772, 2022). "In contrast to the cell culture studies, treatment with single agent BKM120, a pan-PI3K antagonist, or arsenic trioxide, as a GLI antagonist, did not inhibit LSCC tumor growth or GLI1 expression in vivo, whereas combination treatment demonstrated tumor regression and inhibition of GLI1 expression." (PMID 36010600, 2022). "Since both SETD7 and GLI1 mRNA levels were upregulated in A-549 cell line when compared to the non-malignant bronchial epithelial lung cell line BEAS-2B, it is likely that SETD7 activates the SHH signalling in LCa promoting tumour growth and metastasis in vitro and in vivo via GLI3 methylation." (PMID 35326563, 2022). "GLI activation upregulated the expression of VEGF and NRP2 in transgenic tumors of mouse models, which in turn induced α6β1 integrin-mediated activation of RAS/MEK signaling through focal adhesion kinase (FAK) activation to enhance GLI1 expression and promote tumor-initiating or CSC-like properties." (PMID 34572373, 2021). "However, the expression of a GLI1 mutant, with the arginine residue at 597 substituted by lysine (GLI1-R597K mutant), does not lead to the recovery of tumor-forming abilities in GLI1-knockout PDAC cells." (PMID 32859041, 2020). "Thus, the purpose of this work was to evaluate the antitumoral activity of GANT61, a downstream inhibitor of the HH pathway, on the gene and protein expression of HH pathway components (PTCH1, GLI1, GLI2, and GLI3), as well as tumor cell proliferation and death in a metastatic OSCC cell line." (PMID 32846867, 2020). "Additionally, GLI1 expression as related to reduction in tumor mass was not directly evaluated in this analysis." (PMID 32973971, 2020). "Currently it is not known what drives GLI1 transcription in these tumor cells." (PMID 31867038, 2019). "Indeed, the antitumor effects of their inhibition occur most likely through cell-extrinsic mechanisms in the stromal compartment that affect GLI1 expression and alter the secretome of CAFs, leading to the suppression of PDAC growth and tumor-sphere formation in a paracrine manner." (PMID 31244888, 2019). "Unfortunately, and despite the fact that we used adjacent tumor sections, we are currently not able to judge whether GLI1 positive tumor cells are completely devoid of EGFR expression." (PMID 31867038, 2019). "The inhibitory activity on GLI1 was selective in tumor cells but not in normal cells." (PMID 31783569, 2019). "Additionally, it was also described that OPN, a secreted phosphoglycoprotein that is abundant in the tumor microenvironment, induces GLI1 in BC cells through a non-canonical ligand-independent pathway." (PMID 31027259, 2019). "Therefore, the inhibitory effect of Xiaoaiping on tumor growth may be achieved by enhancing the autophagy and apoptosis of HCC cells, as well as reducing its cellular activity via the downregulation of Gli1 and Gli2." (PMID 31341493, 2019). "It remains possible that agents that bind GLI1/2 directly could be used in the tumours that express high levels of these proteins regardless of the presence of activating mutations in the HH pathway." (PMID 30068568, 2018).
tumor (continued). "GLI1 inhibitors, like GANT61, may have a much broader indication than SMO inhibitors because GLI1 is expressed in many tumour cells that do not have an active HH pathway." (PMID 30068568, 2018). "Therefore, observations of only a modest 50% drop in the level of GLI1 RNA in tumour cells treated with high doses of cyclopamine do not support the argument that the HH pathway is driving both GLI1 expression and the growth of such cells." (PMID 30068568, 2018). "IHC analysis confirmed the reduced levels of Ki67, Gli1, and VEGFR2 in FOXC1-silenced xenograft tumors, whereas FOXC1 overexpression upregulated these proliferative and metastatic markers compared with the xenograft tumors from empty vector control tumor group." (PMID 29976975, 2018). "The emerging consensus seems to be that, while such tumours may be targeted by agents that inhibit GLI1, such as GANT61, they are not sensitive to treatment with physiological levels of SMO inhibitors." (PMID 30068568, 2018). "Interestingly, Acta2 and Cnn1 were decreased by 21- and 12-fold, respectively, in stromal Gli1-expressing tumor cells compared with WT, and VIM was not significantly altered." (PMID 27935821, 2017). "Additionally, GLI1, p-STAT3, STAT3, and SOCS3 were detected both in the tumor and the adjacent stromal tissues, indicating that the involvement of these proteins in the tumor microenvironment." (PMID 27275540, 2017). "In consideration of the Shh and Gli-1 results, we can speculate that the decreased MMP-2 and MMP-9 levels may be due to the inhibited activity of the Hh signaling pathway by high intracellular DOX concentrations, thus inhibiting tumor invasion and migration." (PMID 29157266, 2017). "These experiments revealed that the protocol of pretreatment with LDE225 followed by irradiation could efficiently inhibit HL60/ADR and HL60/RX tumor growth in vivo, and the mechanism by which LDE225 sensitizes cells to radiation may be mediated through inhibition of the Gli-1/pAKT/NF-kB pathway." (PMID 27105509, 2016). "Additionally, sample size didn't influence the relationship between Gli-1 expression and tumor size neither." (PMID 27634907, 2016). "To evaluate the role of NANOG on self-renewal and tumor growth independently, we generated stable rescue lines where NANOG expression was decreased in GLI1 overexpressing cells (GLI1+shNANOG) and corresponding empty vector (pCMV+pLKO.1) or GLI1 overexpression only controls (GLI1+pLKO.1)." (PMID 26189795, 2016). "This study revealed a novel non-canonical manner controlling the levels of GLI1 via a menin-mediated epigenetic pathway, and provided a possible mechanism of tumor development of MEN-1 disease, and a rationale for directly inhibiting GLI1 for treating these tumors." (PMID 26343727, 2015). "Knockdown of both SMO and GLI1 in SSM2c and A375 melanospheres and engraftment of SSM2c cells transduced with lentiviral-shSMO and LV-ShGLI1 leads to a drastic decrease in the fraction of ALDH+ cells, reduced clonogenicity and reduced tumour growth, respectively." (PMID 26270676, 2015). "While the balanced physiologic activation of GLI1 regulates differentiation and development of various organs, mutations in HH signaling genes or oncogenic signals upregulate the expression of GLI1 in a non-homeostatic manner (aberrant GLI1) leading to the development of neoplasm." (PMID 26633513, 2015). "Interestingly, silencing GLI1 expression in GLI1-induced tumors did not result in tumor regression, as the cells unexpectedly continued proliferation independent of GLI1." (PMID 26633513, 2015). "However, downregulation of GLI1 did not attenuate the tumor growth at later stages of the tumor development in the same study." (PMID 26633513, 2015).